FGFR2 (fibroblast growth factor receptor 2)
Diseases named in the same sentence as FGFR2 in open-access papers (continued):
Sharing a sentence is not in itself a finding about the gene and the disease.
breast tumors (continued). "The growth inhibition by TKI258 in vivo was accompanied by significantly reduced phosphorylation of FGFR2 and Erk1/2, indicating the dependence of breast tumor growth on activation of FGFR2 and its downstream targets." (PMID 23300950, 2013). "We also compared the FGFR2 mRNA expression in fibroblasts derived from normal skin tissue, normal breast tissue and breast tumor tissue." (PMID 21767389, 2011). "Finally, since the SNPs in intron 2 of FGFR2 are mainly associated with estrogen receptor-positive (ER-positive) breast tumors, we studied a possible correlation between FGFR2 mRNA levels and ER status of the tumor in 50 patients, but could detect none (P = 0.60; logistic regression)." (PMID 21767389, 2011). "This is in agreement with measurements of FGFR2 mRNA expression in total RNA from breast tumor tissue." (PMID 21767389, 2011). "Here we have explored some of the end points of these processes in breast tumors from patients with different FGFR2 mRNA levels in their fibroblasts." (PMID 21767389, 2011). "In the 11 patients from whom we obtained fibroblasts from skin, normal breast tissue and breast tumor tissue, FGFR2 expression levels in the tumor-derived fibroblasts were consistently higher than in the fibroblasts from normal breast tissue." (PMID 21767389, 2011). "Downregulation of FGFR2 protein has been reported in up to 67% of breast tumors, whereas amplification of FGFR2 and upregulation of FGFR2 mRNA expression have been reported in less than 10% of breast tumors." (PMID 21767389, 2011). "FGFR2 and FGF10, the main ligand of FGFR2, are both overexpressed in 5–10% of breast tumors." (PMID 23527311, 2013). "In addition, pharmacological inhibition of FGFR2 kinase activity led to a decrease in the TIC population which resulted in suppression of breast tumor growth." (PMID 23300950, 2013). "We hypothesized that specific private mutations of an activating nature in FGFR2 and FGF10 might influence breast tumor development and growth." (PMID 23527311, 2013). "We also investigated whether the FGFR2+ population is enriched for human breast tumor-initiating cells by monitoring aldehyde dehydrogenase (ALDH) activity since elevated ALDH activity has been shown in normal and malignant human mammary stem cells." (PMID 23300950, 2013). "First, we examined expression levels of FGFR2 in patient-derived breast tumors." (PMID 23300950, 2013). "Also, epithelial breast tumor cells express lower levels of FGFR2 than surrounding normal breast epithelium." (PMID 21767389, 2011). "It is not clear how this might fit with experimental data that suggest FGFR2 is important in increased branching during mammary gland development and in the generation of breast tumour-initiating cells: it is likely that FGFR2 may play distinct roles at different stages of breast development." (PMID 27236187, 2016). "In tissue samples obtained from consecutive surgeries of primary human breast tumors, FGFR1 was most abundantly expressed at the mRNA level, followed by FGFR4 and FGFR2." (PMID 33119860, 2021). "The CNA profile of the primary breast tumour, the bone metastasis and the PDX, were highly similar with focal amplification of FGFR1, FGFR2 and CCND1 and CN gains of CCNE2." (PMID 32792481, 2020). "This refinement of the association between FGFR2 variants and ER-status to HER2-negative disease provides novel insight to potential biological and clinical influence of genetic polymorphisms on breast tumors." (PMID 27764800, 2016). "Quantitative real-time PCR revealed a strong increase (32- to 293-fold) in FGFR2 mRNA levels in 2 of 26 breast tumors (∼8%) compared to a normal breast sample." (PMID 23300950, 2013).
breast tumors (continued). "Unequivocal evidence that paracrine FGF released from breast tumor stroma functions to promote tumorigenesis is lacking, but, intriguingly, we found a strong correlation between FGFR2 and FGF10 mRNA expression levels in the cultured skin fibroblasts." (PMID 21767389, 2011). "Although marked overexpression of FGFR2 has previously been reported in up to 12% of breast tumours, we did not observe this phenomenon in the 40 tumours that we analysed." (PMID 21418638, 2011). "Analysis of RNA-seq databases showed significantly decreased FGFR2 and ITGB1 mRNA levels in breast tumour samples, when compared to non-transformed tissues." (PMID 37191822, 2023).
glioma (27 papers, 2013 to 2025). A benign or malignant brain and spinal cord tumor that arises from glial cells (astrocytes, oligodendrocytes, ependymal cells). "Conversely, in patients diagnosed with glioma, diminished expression of FGFR2 and its IIIb/IIIc splice variants shows a strong inverse correlation with tumor malignancy level, consequently predicting poorer patient survival rates." (PMID 41567627, 2025). "Reduced expression of FGFR2, as well as its IIIb and IIIc isoforms, are associated with a higher tumor grade with poor survival in patients with glioma." (PMID 38255923, 2024). "On the other hand, Ohashi’s study suggested that the decrease or loss of FGFR2 in high-grade gliomas correlates with a high proliferation rate of the tumour and a poor prognosis." (PMID 38473753, 2024). "FGFR2 is involved in gliogenic differentiation, and its activation in glioma cells causes differentiation of brain glioma cells." (PMID 35538578, 2022). "Reduced expression of FGFR2, as well as its IIIb and IIIc isoforms, is associated with a higher tumor grade and poorer survival in glioma patients." (PMID 31337028, 2019). "In gliomas, FGFR2 downregulation is associated with increased proliferation and reduced survival." (PMID 40393028, 2025). "And a decrease or loss of FGFR2 in high-grade gliomas was correlated with poor prognosis." (PMID 37273702, 2023). "In contrast, FGFR2 exhibits reduced expression with increasing glioma grade and correlating with poor prognosis." (PMID 40467542, 2025). "Based on their prognostic relevance in glioma samples, the seven variables age, FGFR2, IDH1, CDK4, CDK6, KIT, and CDKN2A were selected for the construction of the WHO5 risk signature." (PMID 37273702, 2023). "The main massively overexpressed band in LMS4 migrated approximately 20 kDa upper than the overexpressed wild-type FGFR2 from other HG glioma samples, most consistent with the molecular weight of FGFR2-TACC2 (blue arrow)." (PMID 33853673, 2021). "The FGFR2-INA fusion was previously reported in low grade gliomas that drove oncogenesis via MAPK and PI3K/mTOR pathway activation." (PMID 33710807, 2021). "The majority of these patients were FGFR3-TACC3 positive, but we also observed 1 case of a FGFR2-INA fusion that was originally described in gliomas, and 2 novel FGFR fusions, including SLC20A2-FGFR1 and FGFR4-GAPGEFL1." (PMID 33710807, 2021). "Ohashi and co-workers found a correlation of FGFR2 lower expression with increased cancer cell proliferation and poor prognosis in patients with gliomas." (PMID 34830951, 2021). "By contrast, experimental tumors derived from in vivo implantation of C6 glioma cells exhibited decreased tumor growth after inhibition of FGFR2 signaling by a dominant negative construct." (PMID 31337028, 2019). "EGFR, PDGFRA, FGFR1, FGFR2, FGFR4 and MET are frequently amplified, mutated, or fused in high-grade gliomas or in secondary GBMs." (PMID 27385209, 2016). "RTK phospho-arrays were employed to screen activity of co-expressed receptors and our subsequent experiments demonstrated a reduction in FGFR1 and FGFR2 phosphorylation in glioma cell lines." (PMID 25314669, 2014). "However, FGFR2 inhibition reduces tumour growth, indicating a moderating role in glioma progression." (PMID 40467542, 2025). "It has also been used to detect complex CNVs such as JAK1-PAK2, JAK1-PVT1, JAK1-MYOCD, JAK1-TIMM21, USP7-TIMM21, and JAK1-Chr22 CNVs in whole blood-derived ovarian cancer samples, EGFR, CDKN2A, and BRAF CNV in glioma tissues, as well as FGFR2 CNV in colorectal and gastric adenocarcinomas." (PMID 40725150, 2025). "Furthermore, FGFR2 has been shown to directly phosphorylate PTEN on tyrosine 240 in glioma cells which affects PTEN-chromatin interactions independent of PTEN’s phosphatase activity." (PMID 39056803, 2024). "In contrast to FGFR1, FGFR2 expression decreases with the glioma grade." (PMID 38255923, 2024). "FGFR2 fusions and rearrangements have also been found in gliomas." (PMID 37750089, 2023).
glioma (continued). "In contrast to FGFR1, FGFR2 expression decreases with glioma grade." (PMID 31337028, 2019). "Moreover, their whitish aspect suggested a deficiency in angiogenesis when using silenced cells, as previously reported for FGFR1 and FGFR2 activity in glioma cells." (PMID 23696849, 2013). "Other, rarer fusions have also been identified, such as FGFR1-TACC1 and FGFR2-CTNNA3 fusions are rare events predominantly found in IDH-mutant lower-grade gliomas (≤1%)." (PMID 41567627, 2025). "Age, FGFR2, IDH1, CDK4, CDK6, KIT, and CDKN2A were considered vital indicators related to the prognosis and OS time of glioma." (PMID 37273702, 2023). "The results showed that patients in different groups defined by age, FGFR2, IDH1, CDK4, CDK6, KIT, and CDKN2A had significantly different OS in all glioma grades." (PMID 37273702, 2023). "Alterations in CDK4/6, CIC, FGFR2/3/4, FUBP1, KIT, MET, NF1, PEG3, RB1, and NTRK2 were additional factors correlated with the survival of different subtypes of gliomas." (PMID 36998447, 2023). "FGFR2 can also phosphorylate PTEN at Y240, this phosphorylation is frequent in glioma patients with high PTEN and FGFR2 expressions." (PMID 36428706, 2022). "These include FGFR1 tyrosine kinase domain duplication in low grade glioma, FGFR1-TACC1 fusions in extraventricular neurocytoma (EVN), and FGFR2-CTNNA3 fusions in polymorphous low grade neuroepithelial tumor of the young (PLNTY)." (PMID 32085805, 2020). "Some intriguing aspects of the core gene set identified in this study include the well-studied glioma-related genes ANGPT2, CD44, SPP1, STAT3, PDGRFA, and TOP2A (all up-regulated), and BRSK1, DKK3, FGFR2, MAPK9, MEF2C, and PTEN (all down-regulated)." (PMID 29352201, 2018). "Finally, we combined the results of the XGB model and univariate Cox regression analysis to identify age, FGFR2, IDH1, CDK4, CDK6, KIT, and CDKN2A as crucial predictors of prognosis and OS time for glioma patients." (PMID 37273702, 2023). "Several studies have documented that high-grade gliomas show an increased expression of FGFR1, and decreased expression of FGFR2, but in almost all cases, FGFR expression was detected at a global level, and limited or no effort was made to further identify FGFR splice isoforms." (PMID 31337028, 2019).
biliary tract cancer (26 papers, 2014 to 2026). "Recently, several targeted therapies have been investigated in advanced biliary tract cancer (BTC) including inhibitors of genes or pathways such as FGFR2 fusions or rearrangements, IDH1 mutations, and NTRK gene fusions." (PMID 35693217, 2021). "Moreover, precision medicine with targeted therapy, such as targeting isocitrate dehydrogenase-1 mutations and the fibroblast growth factor receptor-2 fusions, is now being used for biliary tract cancer, although this is mainly applicable to intrahepatic CCA and not as commonly for eCCA." (PMID 36826127, 2023). "Together, these insights underscore the central role of FGFR2-directed therapy in precision oncology for biliary tract cancer and provide a framework for optimizing and extending targeted treatment in this molecularly defined disease subset." (PMID 41682001, 2026). "FGFR2 fusions or rearrangements are the most common FGFR alterations in biliary tract cancers and are expressed in 15%-20% of intrahepatic cholangiocarcinomas." (PMID 40013221, 2025). "Tasurgratinib, a selective FGFR1–3 inhibitor, was approved in Japan in 2024 for second-line treatment of FGFR2 fusion-positive biliary tract cancer." (PMID 40565050, 2025). "For example, molecular abnormalities such as IDH1/2 mutations, FGFR2 fusions, and HER-2 overexpression are more common in some types of biliary tract cancer." (PMID 39839773, 2024). "A TOPAZ-1 post hoc analysis found that patients with biliary tract cancer with clinically actionable genomic alterations, including FGFR2 rearrangements, had an OS benefit from first-line durvalumab plus gemcitabine and cisplatin versus chemotherapy alone." (PMID 38838500, 2024). "OS in FGFR2/3 altered and OS in FGFR2 rearranged patients compared to OS in iCCA (*) or Biliary Tract Cancer BTC (#) cases." (PMID 37168376, 2023). "Ponatinib was further evaluated in patients (n = 12) with advanced biliary tract cancer (83.3% iCCA; 16.7% gallbladder) with FGFR2 alterations (83.3% FGFR2 translocations) who received prior chemotherapy." (PMID 37681152, 2023). "For example, in the BITCOIN trial, out of 286 biliary tract cancer cases analyzed, the 24 patients (8.4%) with FGFR2/3 alteration had a better OS compared to FGFR wild-type cases (29.2 vs 14.4 months, p = 0.003)." (PMID 37168376, 2023). "Based on these results, pemigatinib was approved for FGFR2 fusion/rearrangement positive biliary tract cancer by the FDA and MHLW." (PMID 36290850, 2022). "A recent prospective observational study using fluorescent in situ hybridization (FISH) reported that the prevalence of FGFR2 fusion/rearrangement was 5.6% (25/445) in Japanese patients with biliary tract cancer." (PMID 36290850, 2022). "In a phase II study enrolling 107 patients with FGFR2 fusion/rearrangement positive biliary tract cancer who failed prior chemotherapy (FIGHT-202), pemigatinib, an oral inhibitor of FGFR 1–3, demonstrated 35.5% of ORR, which met the predefined ORR of 33%." (PMID 36290850, 2022). "Among biliary tract cancers, studies have shown that FGFR2 gene translocations occur nearly exclusively in the ICC and generally occur in younger patients with a more indolent disease course." (PMID 34945742, 2021). "Driver genes, such as the ERBB2, PIK3CA, IDH1/2, BRCA1/2, and FGFR2 fusion genes, have been identified in gallbladder and biliary tract cancers." (PMID 34573929, 2021). "Another study of 260 Japanese patients with biliary tract cancers (145 ICC) corroborated the importance of driver FGFR2 fusion genes." (PMID 34945742, 2021). "Fibroblast growth factor receptor 2 (FGFR2) rearrangement is expected to be a novel therapeutic target in advanced/recurrent biliary tract cancer (BTC)." (PMID 33106918, 2021). "However, in contrast to previous “all comer”trials, these studies will recruit a genetically more homogenous group ofexclusively iCCA patients, and will help to determine the prognostic and predictivevalue of FGFR2 fusions in biliary tract cancer." (PMID 32983265, 2020).
biliary tract cancer (continued). "DNA and RNA validation of FGFR2 fusions in 3 patients with advanced sporadic biliary tract cancer." (PMID 24550739, 2014). "Currently potential therapeutic targets have been identified in nearly 40% of biliary tract cancers, with the most promising in iCCA patients including isocitrate dehydrogenase 1 (IDH1) and fibroblast growth factor receptor 2 (FGFR2)." (PMID 37168376, 2023). "Targeted therapies (ie, FGFR2 and IDH1 inhibitors) have a potential role in the second-line setting for advanced biliary tract cancer." (PMID 33798493, 2021). "In biliary tract cancers (BTC), FGFR2 fusions are predominantly observed in iCCA patients." (PMID 39697545, 2024). "Whereas in iCC alterations in genes dedicated as ESCAT I/II (FGFR2 fusion, BRAF-V600E mut., Her2neu amplification, IDH1 mut., MSI and NTRK Fusion) according to the latest ESMO guidelines for molecular testing in biliary tract cancer were more frequent than in eCC (27.5% vs. 10.5%; p = 0.0093)." (PMID 37723192, 2023). "However, a pitfall of this study is that no specific OS data on FGFR2 fusions in iCCA were presented, with data from all biliary tract cancer being included." (PMID 37168376, 2023).
hepatocellular carcinoma (26 papers, 2012 to 2026). A malignant tumor that arises from hepatocytes. "Conditional FGFR2 gene knockout and low or reduced FGFR2 expression were linked with increased sensitivity to chemically induced squamous cell carcinoma of the skin, more aggressive growth of hepatocellular carcinoma, and increased epithelial-to-mesenchymal transition." (PMID 32971804, 2020). "PTBP1 converts oncogenic FGFR2‐IIIb to pro‐carcinogenic FGFR2‐IIIc isoforms by modulating the selective splicing of FGFR2, which ultimately promotes hepatocellular carcinoma development." (PMID 40579921, 2025). "In the present study, we examined the immunohistochemical expression of FGFR2 as a surrogate marker for FGFR2 genetic alterations in cHCC-CCAs and other types of primary liver carcinomas." (PMID 38532197, 2024). "Patients with FGFR2-BicC family RNA-binding protein 1-combined hepatocellular carcinoma showed decreased tumor volumes." (PMID 34639155, 2021). "This is in line for instance with hepatocellular carcinoma (HCC) where recent data suggest high expression of FGFR2 and FGFR3 as potential biomarkers for infigratinib response." (PMID 31527449, 2019). "FGFR2 fusions were characteristic of hepatobiliary/hepatocellular cancer (1.7%)." (PMID 37537783, 2023). "Likely in hepatocellular carcinoma, specific lncRNAs recruit polycomb proteins (EZH2, SUZ12) and histone demethylases (KDM2A) to FGFR2 loci, facilitating exon IIIb inclusion and favoring tumor-suppressive isoform expression." (PMID 41584352, 2026). "PLOD2 was related to HNSCC, hepatitis C, hepatocellular carcinoma, renal cell carcinoma, and CTLA4 inhibitory signaling while PLOD3 was linked to basal cell carcinoma, renal cell carcinoma, ncRNAs involved in WNT signaling in hepatocellular carcinoma, and FRS-mediated FGFR2 signaling." (PMID 36820030, 2023). "Moreover, upregulation of cancer-specific isoforms of TP73, CDH17, KLF6, FGFr2, FGFR3, DNMT3b3, and OPN has been reported in human hepatocellular carcinoma (HCC) and promoted cell cycle progression, proliferation, invasion and metastasis." (PMID 35463320, 2022). "STAT1 was significantly positively correlated with PD1 (r = 0.448), PD-L1 (r = 0.444), CTLA-4 (r = 0.436), FGFR2 (r = 0.354), FGFR3 (r = 0.36), and IDO1 (r = 0.387) in HCC, suggesting that targeting STAT1 may improve the efficacy of immunotherapy for hepatocellular carcinoma." (PMID 35646925, 2022). "FGFR2 expression, which is a surrogate marker for FGFR2 genetic alterations, was immunohistochemically assessed in the liver sections from 75 patients with cHCC-CCA, 35 with small duct-type iCCA, 30 with large duct-type iCCA, and 35 with hepatocellular carcinoma (HCC)." (PMID 38532197, 2024).